PSORS1C2 (psoriasis susceptibility 1 candidate 2)
Synonyms: C6orf17; SPR1
Tractability: Antibody: UniProt places it where antibodies can reach, with high confidence; UniProt predicts a signal peptide or a membrane-spanning region; its Gene Ontology location is reachable by antibodies, with medium confidence.
Safety:
Unwanted effects reported when the protein is acted on. In parentheses: how it was acted on, where the effect was seen, and who reports it.
DRESS Syndrome or Stevens-Johnson Syndrome (source: ClinPGx)
Gene: Protein-coding gene on chromosome 6 (31,137,534 to 31,139,066, reverse strand). Ensembl gene ENSG00000204538.
Subcellular location: Secreted
Gene Ontology:
Molecular function: protein binding
Cellular component: extracellular region
Genetic constraint (gnomAD): Loss-of-function variants: 12 observed, 10.57 expected, observed/expected ratio (o/e) 1.13, 90% interval 0.72 to 1.76. The upper end of that interval is the gene's LOEUF score, 1.76, which puts it in group 6 of 6, group 1 being the genes least tolerant of losing a copy. Missense variants: 173 observed, 147.21 expected, observed/expected ratio (o/e) 1.18, 90% interval 1.04 to 1.33. Synonymous variants: 71 observed, 61.51 expected, observed/expected ratio (o/e) 1.15, 90% interval 0.95 to 1.41.
Homologues: Orthologues: chimpanzee PSORS1C2 (96% identical), macaque PSORS1C2 (94% identical), pig PSORS1C2 (79% identical), rabbit PSORS1C2 (76% identical), guinea pig PSORS1C2 (71% identical), rat Psors1c2 (70% identical), mouse Psors1c2 (68% identical).
Diseases named in the same sentence as PSORS1C2 in open-access papers:
PSORS1C2 is named in the same sentence as 9 diseases in open-access papers, as found by Europe PMC text mining. Sharing a sentence is not in itself a finding about the gene and the disease. The quoted sentences say what the papers report.
schizophrenia (2 papers, 2020 to 2021). A major psychotic disorder characterized by abnormalities in the perception or expression of reality. "Three human genes, ADCYAP1, PSORS1C2, and BTNL2, are associated with neuronal phenotypes, such as schizophrenia." (PMID 34542594, 2021).
depression (1 paper, 2020). "Three replicated loci were previously reported (ITIH3, FHIT, BAG5), but the other seven (ZNF804A, MIR3143, PSORS1C2, STK19, SPATA31D1, RTN1, TCF4) were novel for depression." (PMID 30626913, 2020).
follicular lymphoma (1 paper, 2011). Follicular lymphoma is a form of non-Hodgkin lymphoma characterized by a proliferation of B cells whose nodular structure of follicular architecture is preserved. "The locus associated with total WBC count on chromosome 6p21 contains genes associated with follicular lymphoma (CHCG22), progression of HIV-1 infection (CDSN, PSORS1C1 and PSORS1C2) and psoriasis (CCHCR1, PSORS1C1 and PSORS1C2)." (PMID 21738480, 2011).
hypotrichosis (1 paper, 2020). A congenital condition, usually due to genetic aberrations, that is characterized by a lack of hair growth on the head and/or body. "Although the deletion encompasses several other genes (C6orf15, PSORS1C1, PSORS1C2, CCHCR1 and part of TCF19), these patients show a phenotype resembling that of PSD without hypotrichosis." (PMID 31663161, 2020).
leprosy (1 paper, 2021). Leprosy is a chronic infectious disease affecting primarily the skin and peripheral nervous system. "We identified mutations in four genes (IL18R1, BCL10, CDSN, and PSORS1C2) as candidates for functional mediators of leprosy susceptibility." (PMID 34879060, 2021).
PSORS1C2 also shares sentences with these, for which no sentence is quoted: HIV-1 infection (1 paper); inflammatory skin disease (1); periodontitis (1); psoriasis (1).